BTK (Bruton tyrosine kinase)
Diseases named in the same sentence as BTK in open-access papers (continued):
Sharing a sentence is not in itself a finding about the gene and the disease.
aspergillosis (5 papers, 2020 to 2024). Aspergillosis is an infection, growth, or allergic response caused by the Aspergillus fungus. "Here, we studied BTK-dependent neutrophil responses against A. fumigatus in diverse human populations with inherited BTK deficiency and pharmacological BTK blockade and in a mouse model of aspergillosis." (PMID 38696257, 2024). "Taken together, these data demonstrate the beneficial effects of GM-CSF on neutrophil antifungal function in the setting of BTK deficiency and inform a potential translational strategy to bypass the BTKi-driven neutrophil defects during aspergillosis." (PMID 38696257, 2024). "Here, we suggest that neutrophil dysfunction is important to BTK inhibition–associated aspergillosis." (PMID 38713531, 2024). "Lyz2-Cre/Btkfl/fl mice were susceptible to aspergillosis (75% mortality versus 28% in littermate control mice), underscoring the critical contribution of BTK-expressing myeloid phagocytes in anti-Aspergillus protection." (PMID 38696257, 2024). "We then investigated whether BTK deficiency affects neutrophils qualitatively by impairing their antifungal effector functions to promote susceptibility to aspergillosis." (PMID 38696257, 2024). "We next asked whether BTK deficiency impairs neutrophil influx or survival in the lung to increase susceptibility to pulmonary aspergillosis, since BTK has been shown to promote neutrophil recruitment in the liver, muscle, and peritoneal cavity during sterile inflammation." (PMID 38696257, 2024). "Treatment of WT mice with the BTKi ibrutinib or acalabrutinib — a second-generation BTKi that features greater selectivity for BTK and lacks ITK or TEC targeting — phenocopied the increased susceptibility to pulmonary aspergillosis observed in Btk–/– mice." (PMID 38696257, 2024). "Taken together, these data show that BTK promotes protection against pulmonary aspergillosis by exerting direct effects on myeloid phagocytes and primarily neutrophils." (PMID 38696257, 2024). "We describe a previously unappreciated role for Bruton’s tyrosine kinase (BTK) in fungal immune surveillance against aspergillosis, an unforeseen complication of BTK inhibitors (BTKi) used for treating B cell lymphoid malignancies." (PMID 38696257, 2024). "A key role for BTK in macrophage responses during experimental pulmonary aspergillosis has been reported." (PMID 33777941, 2021). "Moreover, because aspergillosis in the setting of BTKi treatment has a high predilection for extrapulmonary spread, particularly to the central nervous system, the role of BTK in promoting microglial anti-Aspergillus responses merits further investigation." (PMID 38696257, 2024). "Interestingly, there is a proclivity of disseminated Aspergillus infection to the CNS in patients treated with a BTK inhibitor, with 40%–60% of IBT-associated aspergillosis presenting cerebrally." (PMID 38713531, 2024). "Thus, to directly assess whether BTK-dependent protection against aspergillosis relies on BTK expression in myeloid phagocytes, we generated mice with myeloid phagocyte-specific conditional ablation of Btk by crossing Btkfl/fl with Lyz2-Cretg mice." (PMID 38696257, 2024). "BTK activation led to calcineurin-NFAT signaling, which was considered crucial for orchestrating neutrophil recruitment during pulmonary aspergillosis." (PMID 33777941, 2021).
asthma (5 papers, 2021 to 2025). "BTK signaling is also an essential regulator of the pro-inflammatory process in the lungs, which makes disrupting BTK a promising strategy against chronic pulmonary inflammatory diseases, including chronic obstructive pulmonary disease and asthma." (PMID 36183125, 2022). "BTK inhibitors could be useful to treat pathological mast cell responses of asthma." (PMID 36140430, 2022).
atherosclerosis (5 papers, 2021 to 2024). A disease characterized by the build-up of fatty material and calcium deposition in the arterial wall resulting in partial or complete occlusion of the arterial lumen. "Gut microbiota-associated macrophage genes (PLEK, IRF8, CD68, CCR1, and BTK) may be implicated in the pathogenesis of atherosclerotic plaques and could serve as diagnostic markers to aid patients with atherosclerosis." (PMID 38716195, 2024). "To provide targeted diagnostic assistance for atherosclerosis patients, we constructed a proprietary Nomogram model based on the expression of PLEK, IRF8, BTK, CCR1, and CD68." (PMID 38716195, 2024). "In another study, using a macrophage-mediated model of atherosclerosis, bioinformatics results indicated that BTK is related to oxidative stress, ER stress, and inflammation, thus identifying BTK as a potential therapeutic target." (PMID 35054524, 2022). "To further investigate the potential role of gut microbiota-associated core macrophage genes in atherosclerosis, we applied unsupervised clustering methods based on the expression of PLEK, IRF8, BTK, CCR1, and CD68 to classify atherosclerosis patients into groups A and B." (PMID 38716195, 2024). "We further evaluated the diagnostic sensitivity and specificity of both genes by ROC curves, and both genes had good diagnostic value in the experimental set: BTK (AUC = 0.909) and ITGAL (AUC = 0.937) in atherosclerosis; BTK(AUC = 0.840) and ITGAL(AUC = 0.873)in periodontitis." (PMID 37369700, 2023). "BTK inhibitors may be potential agents for the treatment of atherosclerosis by regulating macrophage polarization, phagocytosis and secretion of pro-inflammatory factors." (PMID 37369700, 2023). "Leveraging machine learning algorithms, we have identified PLEK, IRF8, BTK, CCR1, and CD68 as evaluative markers to assist in the diagnosis of atherosclerosis." (PMID 38716195, 2024). "We verified the expression levels of two crosstalk genes separately in the validation dataset, and the results showed that BTK and ITGAL were upregulated in both atherosclerosis and periodontitis." (PMID 37369700, 2023). "BTK and ITGAL were found to be the most important cross-signaling genes between periodontitis and atherosclerosis by WGCNA combined with immune cell analysis." (PMID 37369700, 2023). "We then further validated the diagnostic effect of both genes in the validation dataset: BTK (AUC = 0.861) and ITGAL (AUC = 0.832) in atherosclerosis; and BTK (AUC = 0.810) and ITGAL (AUC = 0.835) in periodontitis." (PMID 37369700, 2023). "They concluded that BTK inhibition alone did not affect MC activation in early and advanced stage atherosclerosis, despite the systemic biological effect on follicular B cell maturation." (PMID 38289515, 2024).
B-cell neoplasm (5 papers, 2021 to 2025). A group of heterogeneous lymphoid tumors generally expressing one or more B-cell antigens or representing malignant transformations of B-lymphocytes. "Targeting BTK with proteolysis-targeting chimeras (PROTACs) represents a promising strategy to overcome resistance to BTKi in B cell neoplasms." (PMID 38542207, 2024). "BTK is widely expressed in B cell neoplasms, and the clinical interventions are generally performed by inhibiting the kinase activity of BTK." (PMID 36536188, 2022). "Another drug that has shown significant activity in altering the function of MDSCs is ibrutinib, which targets Bruton’s tyrosine kinase (BTK) and is widely used for the clinical treatment of B cell neoplasms." (PMID 33925214, 2021). "Moreover, targeting BTK with proteolysis-targeting chimeras (PROTACs) represents a promising strategy to overcome resistance to BTKi in B cell neoplasms." (PMID 38542207, 2024).
chronic spontaneous urticaria (5 papers, 2021 to 2025). "Therefore, small-molecule BTK inhibitors, such as fenebrutinib and remibrutinib are currently in stage 2 and 3 clinical trials for chronic spontaneous urticaria." (PMID 35744079, 2022). "Bruton’s tyrosine kinase (BTK) is crucial for FcεRI-mediated mast cell activation and essential for autoantibody production by B cells in chronic spontaneous urticaria (CSU)." (PMID 34750553, 2021).
cryptococcosis (5 papers, 2016 to 2025). An acute or chronic, localized or disseminated infection by Cryptococcus neoformans. "This indicates that therapies targeting BTK could potentially increase the risk of cryptococcosis." (PMID 40276403, 2025). "For instance, we have found an association with ibrutinib therapy and disseminated cryptococcosis in human B cell malignancy patients, but precise studies with either BTK-knockout or ibrutinib-treated mice showed no impact on cryptococcosis." (PMID 38127685, 2023).
lung fibrosis (5 papers, 2021 to 2024). "As lung fibrosis is a major cause of death in SSc patients, we also investigated the effect of the BTK inhibitor on lung histopathologic changes, including inflammation, airspace dilation, fibrosis, and vasculitis." (PMID 35874767, 2022). "Previous studies indicate that ibrutinib, a first-generation small molecule inhibitor of BTK, ameliorates pulmonary fibrosis by inhibiting inflammation." (PMID 37630287, 2023). "Previous studies have demonstrated that targeting EGFR and BTK may be an effective method to mediate the development of pulmonary fibrosis." (PMID 36949426, 2023). "Considering the significant role of B cells (and myeloid cells) in the development of SSc, we examined the effect of BTK inhibition on both skin and lung fibrosis in a BLM-induced mouse model of this disease, as well as in two additional mouse models of end organ inflammation." (PMID 35874767, 2022). "Moreover, further studies are needed to determine whether avitinib affects other signalling pathways related to pulmonary fibrosis, such as the recognized targets of EGFR and BTK." (PMID 36949426, 2023). "In addition, adoptive transfer of topo I-APC+ topo I-PE+ CD19+ cells from the topo I-induced SSc model mice treated with the BTK inhibitor failed to induce skin and lung fibrosis in non-immunized WT mice." (PMID 34854378, 2021). "However, ibrutinib may have an off-target effect in a mice pulmonary fibrosis model, which could not represent the role of BTK in organ fibrosis." (PMID 37630287, 2023). "Since lung fibrosis was not prominent in BLM-SSc mice, we were not able to assess the impact of BTK inhibition on this phenotype." (PMID 35874767, 2022).
pancreatic ductal adenocarcinoma (5 papers, 2019 to 2024). An infiltrating adenocarcinoma that arises from the epithelial cells of the pancreas. "The use of Ibrutinib as a Bruton tyrosine kinase (BTK) inhibitor has shown success in the treatment of pancreatic ductal adenocarcinoma." (PMID 35746487, 2022). "Another effect is the activation of Bruton’s tyrosine kinase (BTK), which inhibition by ibrutinib stimulates macrophage polarization, myeloid cell infiltration reduction and increase in CD8 + T cells infiltration in murine pancreatic ductal adenocarcinoma (PDAC)." (PMID 31998254, 2019).
pulmonary hypertension (5 papers, 2021 to 2025). Increased pressure within the pulmonary circulation due to lung or heart disorder. "For example, cardiotoxicity caused by ALK, ROS1, EGFR-TKIs; aortic coarctation caused by VEGF-TKI; pulmonary hypertension caused by ALK-TKI, interstitial pneumonia caused by EGFR/ALK TKIs, infection caused by BTK inhibitors and other adverse reactions." (PMID 36761953, 2023). "Mice with enhanced B-cell activation due to B-cell-specific overexpression of the B-cell receptor (BCR) signalling molecule Bruton’s tyrosine kinase (BTK) were subjected to lung injury and examined for several pulmonary hypertension (PH) indices." (PMID 33963088, 2021). "Additionally, in the context of acute lung injury and pulmonary hypertension, BTK inhibitors have been found to markedly enhance anti-inflammatory polarization of macrophages." (PMID 40263985, 2025). "The overexpression of BTK-induced spontaneous germinal center formation and production of autoantibodies in CD19-hBTK transgenic mice, and moreover, induced pulmonary hypertension through activation of BCR signaling in pulmonary injury mice." (PMID 36277750, 2022). "Macrophage accumulation and activation contribute to the development of pulmonary arterial hypertension (PAH), while Bruton's tyrosine kinase (BTK) is an important regulator for the activation and polarization of macrophage." (PMID 36071873, 2022).
anaphylaxis (4 papers, 2020 to 2025). An acute hypersensitivity reaction that occurs from exposure to an allergen. "The role of BTK in IgE-mediated pathways opens possibilities for a more targeted anaphylaxis treatment." (PMID 40802080, 2025). "Like BTK inhibitors, clinical trials are needed to demonstrate safety and efficacy for using Syk inhibitors to prevent food-induced anaphylaxis." (PMID 33391286, 2020). "While foods are a very common cause of anaphylaxis, regardless of the inducing allergen, all IgE-mediated anaphylaxis in humans is mediated by the FcεRI pathway, of which BTK is an essential kinase." (PMID 37384412, 2023).
chronic lymphoid leukemia (4 papers, 2021 to 2025). "Ibrutinib inhibits BTK signaling in B-cells and revolutionized the prognosis of chronic lymphoid leukemia." (PMID 34099830, 2021). "In recent years, BTK inhibitors, for instance Ibrutinib and Acalabrutinib (ACP-196), have achieved success in the treatment of lymphocytic leukemia, whereas their clinical activity against solid tumors is limited." (PMID 37033615, 2023).
head and neck squamous cell carcinoma (4 papers, 2020 to 2023). A squamous cell carcinoma that arises from any of the following anatomic sites: lip and oral cavity, nasal cavity, paranasal sinuses, pharynx, larynx, and salivary glands. "BTK encodes Bruton’s Tyrosine Kinase and plays an oncogenic role on head and neck squamous cell carcinoma, promoting epithelial–mesenchymal transition processes and cancer stem cell enrichment." (PMID 38093298, 2023). "Here, we describe the expression of Bruton’s Tyrosine Kinase (BTK) in head and neck squamous cell carcinoma (HNSCC) cell lines as well as in primary HNSCC samples." (PMID 36612306, 2023). "The present study aims to investigate the expression of BTK isoforms in head and neck squamous cell carcinoma (HNSCC)." (PMID 36612306, 2023). "Therefore, we aimed to investigate whether BTK isoforms are also expressed in head and neck squamous cell carcinoma (HNSCC) and further the molecular and cellular consequences of BTK expression for HNSCC tumorigenesis." (PMID 36612306, 2023). "Regarding tumor-infiltrating B cells, Bregs from head and neck squamous cell carcinoma (HNSCC) patients produced adenosine to dampen the phosphorylation of Bruton’s tyrosine kinase (BTK) and Ca2+ influx in effector B cells; thus adenosine signaling may be a possible therapeutic target in HNSCC." (PMID 33193391, 2020). "We recently discovered the expression of two oncogenic isoforms of Bruton’s Tyrosine Kinase (BTK) in head and neck squamous cell carcinoma (HNSCC), Btk-p80 and BTK-p65." (PMID 37685940, 2023).
influenza (4 papers, 2020 to 2022). An acute viral infection of the respiratory tract, occurring in isolated cases, in epidemics, or in pandemics; it is caused by serologically different strains of viruses (influenzaviruses) designated A, B, and C, has a 3-day incubation period, and usually lasts for 3 to 10 days. "More broadly, our findings raise the prospect that the morbidity of other disease states associated with macrophage activation, including severe influenza infections, may similarly depend on BTK function, supporting clinical trial evaluation of BTK inhibitors in these clinical settings as well." (PMID 32503877, 2020). "BTK inhibition was shown to protect against lethal influenza-induced acute lung injury in mice." (PMID 33791689, 2021). "Moreover, in a mouse influenza model, BTK inhibition decreased inflammatory mediators and rescued mice from lethal acute lung injury, suggesting that it may mitigate virally-induced lung damage driven by excessive inflammation." (PMID 32503877, 2020). "Ibrutinib, the world’s first listed BTK inhibitor, has been shown to have a therapeutic effect on coronavirus-induced ALI in the clinic, and it exhibited a mitigating effect on influenza-induced ALI in animal models." (PMID 36362264, 2022).
neuropathy (4 papers, 2022 to 2025). A disorder affecting the nervous system that manifests with pain, tingling, numbness, and/or muscle weakness. "Emerging clinical data indicate that BTK inhibitors show therapeutic potential in the treatment of patients affected by anti-MAG antibody neuropathy, as evidenced by observations within studies of WM patients." (PMID 40351903, 2025). "There is a class IV evidence study showing that BTK inhibitors can improve anti-MAG-related neuropathy." (PMID 40351903, 2025). "Preliminary positive data on the BTK inhibitor, ibrutinib, in patients with anti-MAG antibody neuropathy and a specific mutational profile (MYD88L265P mutation, wild-type CXCR4 gene) need further confirmation on larger populations." (PMID 35349079, 2022). "A second study from Japan explored the role of tirabrutinib, a second-generation BTK inhibitor, for anti-MAG neuropathy." (PMID 40351903, 2025). "The BTK inhibitors (ibrutinib, zanubrutinib, rilzabrutinib) have a potential therapeutic role in B-cell-mediated diseases other than anti-MAG antibody neuropathy, given their good profile (oral administration and favorable safety profile)." (PMID 35349079, 2022).
Obesity (4 papers, 2019 to 2025). Accumulation of substantial excess body fat. "By applying this computational framework to MetSyn, we identify the BTK inhibitor ibrutinib as a candidate drug for lowering the chronic inflammatory condition associated with obesity." (PMID 31740673, 2019). "Here the authors’ integrative network analysis suggests BTK inhibitor ibrutinib to be a promising treatment through its obesity-associated inflammation lowering effect." (PMID 31740673, 2019). "Decreased myeloid cells recruitment has also been reported in other inflammatory models: RA, obesity and cerebral ischaemia, when BTK had been systemically inhibited with BTK inhibitors." (PMID 34897650, 2022). "Given the important role of inflammation in the alteration of adipose tissue biology in obese patients, we investigated the relationship between BTK and the immune system in obesity using public datasets." (PMID 31740673, 2019). "Additional experiments are warranted to further investigate the effect of BTK inhibitors in obesity and the possible benefits for patients with metabolic syndrome." (PMID 31740673, 2019). "In addition to B cells, BTK is also expressed by macrophages, known key players in the development of the obesity-related chronic inflammation and insulin resistance." (PMID 31740673, 2019). "In addition to macrophages, B cells themselves have been implicated in adipose tissue inflammation and insulin resistance, providing additional support for BTK involvement in obesity-related inflammation." (PMID 31740673, 2019). "Bruton's tyrosine kinase (BTK) is highly expressed in monocytes and macrophages and regulates NF‐κB and NLRP3 inflammasome activity; both propagate metabolic inflammation in diet‐induced obesity." (PMID 32608058, 2020).
psoriasis (4 papers, 2019 to 2023). An autoimmune condition characterized by red, well-delineated plaques with silvery scales that are usually on the extensor surfaces and scalp. "They point to the possibility of using BTK as a therapeutic target in psoriasis because the use of a BTK inhibitor (Ibrutinib) allows a reduction in the level of oxidative stress." (PMID 32867343, 2020). "The psoriasis lesion samples showed decreased expression of BTK and TNFRSF1B compared to controls." (PMID 33324666, 2020).